IGLC7 (immunoglobulin lambda constant 7)
Description:
Constant region of immunoglobulin light chains. Immunoglobulins, also known as antibodies, are membrane-bound or secreted glycoproteins produced by B lymphocytes. In the recognition phase of humoral immunity, the membrane-bound immunoglobulins serve as receptors which, upon binding of a specific antigen, trigger the clonal expansion and differentiation of B lymphocytes into immunoglobulins-secreting plasma cells. Secreted immunoglobulins mediate the effector phase of humoral immunity, which results in the elimination of bound antigens. The antigen binding site is formed by the variable domain of one heavy chain, together with that of its associated light chain. Thus, each immunoglobulin has two antigen binding sites with remarkable affinity for a particular antigen. The variable domains are assembled by a process called V-(D)-J rearrangement and can then be subjected to somatic hypermutations which, after exposure to antigen and selection, allow affinity maturation for a particular antigen.
Gene: Immunoglobulin constant (C) gene on chromosome 22 (22,922,594 to 22,923,034, forward strand). Ensembl gene ENSG00000211685.
Subcellular location: Secreted; Cell membrane
Genetic constraint (gnomAD): Missense variants: 91 observed, 82.14 expected, observed/expected ratio (o/e) 1.11, 90% interval 0.93 to 1.32. Synonymous variants: 31 observed, 33.09 expected, observed/expected ratio (o/e) 0.94, 90% interval 0.7 to 1.26.
Homologues: Orthologues: chimpanzee IGLC7 (97% identical), mouse Iglc1 (71% identical), rabbit IGLL1 (69% identical), rat Iglc1 (67% identical), mouse Iglc4 (65% identical), mouse Iglc3 (63% identical), mouse Iglc2 (61% identical). Paralogues in human: IGLC1 (93% identical), IGLC2 (93% identical), IGLC3 (92% identical), IGLL5 (92% identical), IGLL1 (83% identical), IGKC (36% identical), IGHA2 (35% identical), IGHM (35% identical), IGHA1 (33% identical), IGHG1 (32% identical), IGHG2 (32% identical), IGHG3 (32% identical), and 65 more.
Diseases named in the same sentence as IGLC7 in open-access papers:
IGLC7 is named in the same sentence as 7 diseases in open-access papers, as found by Europe PMC text mining. Sharing a sentence is not in itself a finding about the gene and the disease. The quoted sentences say what the papers report.
cervical cancer (1 paper, 2025). A primary or metastatic malignant neoplasm involving the cervix. "Additionally, Immunoglobulin lambda (Igλ), including IGLC7, was enriched in our disease analysis and has been reported in the literature as correlated with cervical cancer tissues." (PMID 40457720, 2025).
COVID-19 (1 paper, 2022). A disease caused by infection with severe acute respiratory syndrome coronavirus 2. "Also, according to IPA analysis, some of them have been associated with viral infection (APOD, APOH, SERPINA1), severe COVID-19 (APOD, APOH, PCYOX1), or leukocyte migration (APOD, IGHV3-13, IGHV3-23, SERPINA1, IGLC7, IGLV3-21)." (PMID 35397534, 2022).
tumor (3 papers, 2023 to 2026). "Except for IGLC4, IGLC5, and IGLC7, the expressions of 4 IGLCs were positively correlated with infiltration scores of some tumor-infiltrating immune cells respectively." (PMID 37784026, 2023). "The expressions of IGLC5 and IGLC7 had significant difference in different pathologic metastasis (M), one of tumor, node, and metastasis (TNM) staging system, categories of CESC." (PMID 37784026, 2023). "Next-generation sequencing (NGS) analysis revealed copy number loss of SMARCB1 and a novel GSTT1::IGLC7 fusion in the tumor, while no other gene rearrangements, including those involving EWSR1, NR4A3, or FUS, were detected." (PMID 42052495, 2026). "Tumor stemness was negatively correlated with the expressions of 4 IGLCs (IGLC1, IGLC2, IGLC3, and IGLC7) respectively in CESC tissues." (PMID 37784026, 2023). "Except for IGLC4, IGLC5, and IGLC7, 4 IGLC (IGLC1, IGLC2, IGLC3, and IGLC6) expressions were positively correlated with infiltration scores of 6 tumor-infiltrating immune cells (B cell, T cell CD4, T cell CD8, neutrophil, macrophage, and DC)." (PMID 37784026, 2023). "In DNAss database, we found that tumor stemness was negatively correlated with the expressions of IGLC1 (r = -0.14, P = 0.02), IGLC2 (r = -0.13, P = 0.02), IGLC3 (r = -0.13, P = 0.02), and IGLC7 (r = -0.14, P = 0.01) respectively in CESC tissues." (PMID 37784026, 2023).
IGLC7 also shares sentences with these, for which no sentence is quoted: Burkitt lymphoma (1 paper); liver cirrhosis (1); malignant lymphoma (1); viral infection (1).